HAT1 (histone acetyltransferase 1)
Diseases named in the same sentence as HAT1 in open-access papers (continued):
Sharing a sentence is not in itself a finding about the gene and the disease.
liver cancer (6 papers, 2019 to 2025). An epithelial or non-epithelial malignant neoplasm that arises from the liver. "The risk score calculated by the expression value of HDAC1, HDAC2, HDAC4, HDAC11, HAT1, and SIRT6 was an independent risk factor for liver cancer." (PMID 36124029, 2022). "For example, HAT1 was found to promote liver cancer cell proliferation and induce cisplatin resistance." (PMID 34564701, 2021). "It has been well documented that HAT1 is an important determinant in the regulation of the proliferation of esophageal and liver cancer cells in vivo and in vitro." (PMID 30709380, 2019). "HAT1 is overexpressed in multiple types of solid tumors, including esophageal, lung cancer and liver cancer, and acts as an oncoprotein to promote tumorigenesis." (PMID 30709380, 2019). "HAT1 has been shown to bind hepatitis B core protein (HBc) via long non-coding RNAs (lncRNA) highly upregulated in liver cancer (HULC) that act as a scaffold in the complex of HAT1/HULC/HBc, which is required for viral replication of HBV cccDNA allowing chromatin assembly by histone acetylation." (PMID 37048148, 2023).
lung carcinoma (6 papers, 2017 to 2023). "Studies with lung cancer cells have demonstrated that the HAT1 and Fas expression levels are lower than those in normal lung cells, and these expression levels are positively correlated." (PMID 37107673, 2023). "The effect of the three aptamers against HAT1 on cell viability was studied in three lung cancer cell lines: A549, H1650 (adenocarcinoma), and SW900 (squamous carcinoma)." (PMID 36612223, 2022). "Histone acetyltransferase 1 (HAT1) has recently been reported to be highly expressed in some tumors, such as lung carcinoma." (PMID 34323404, 2021). "However, in some cancers, such as lung cancer and melanoma, the downregulation of HAT1 contributes to apoptosis and therapy resistance." (PMID 37107673, 2023). "In addition, HAT1 expression was downregulated in LC cells, which contributed to lung cancer (LC) pathogenesis." (PMID 37763801, 2023). "The restoration of HAT1 expression restores Fas expression and induces lung cancer cell apoptosis." (PMID 37107673, 2023). "In addition, this aptamer is also shown to inhibit the acetyltransferase activity of HAT1 in these lung cancer cells." (PMID 36612223, 2022). "When cells were treated with the apHAT610 aptamer at the stated concentration (2 × IC50), a statistically significant reduction in HAT1 activity, measured by histone H4 acetylation and HAT1 protein levels, was observed in lung cancer cell lines 24 h post-transfection." (PMID 36612223, 2022). "HAT1 has also been shown to induce apoptosis by upregulating Fas expression in lung cancer cells." (PMID 32371878, 2020).
melanoma (5 papers, 2020 to 2023). A malignant, usually aggressive tumor composed of atypical, neoplastic melanocytes. "We attempted to determine the mechanism through which phospho-ERK1/2 levels were elevated following the loss of HAT1 expression in BRAF-mutant melanoma cells." (PMID 32371878, 2020). "Taken together, these results demonstrated that the loss of HAT1 expression resulted in acquired BRAFi resistance in melanoma cells." (PMID 32371878, 2020). "In HAT1-KO melanoma cells, genes associated with other signaling pathways were also upregulated, including Hedgehog, notch, cell cycle-apoptosis, chromatin modification, and driver genes." (PMID 32371878, 2020). "In this study, we investigated the role played by HAT1 in the regulation of BRAFi resistance in melanoma cells and showed that the loss of HAT1 expression contributed to the development of BRAFi resistance." (PMID 32371878, 2020). "We observed that HAT1-KO melanoma cells showed complete loss of HAT1 protein expression." (PMID 32371878, 2020). "In this study, we examined whether the loss of HAT1 expression confers BRAFi resistance in melanoma cells." (PMID 32371878, 2020). "Thus our study indicates that loss of HAT1 is one of the crucial mechanism that drives BRAFi resistance in melanoma." (PMID 32371878, 2020). "A previous study showed that HAT1 enhances the efficacy of JQ-1 in treating melanoma cell lines; however, HAT1 was expressed at a high level in ALIS I." (PMID 37513949, 2023). "In this study, we sought to cluster melanoma cells and patients into acetylation-immune subtypes (ALISs) based on the specific roles of HAT1 and PD-L1 in cancer treatment." (PMID 37513949, 2023). "The expression of HAT1 can be decreased by ascorbate through ten-eleven translocation (TET)-mediated DNA hydroxymethylation in melanoma cell lines and mouse models." (PMID 37513949, 2023). "In melanoma, HAT1 was shown to catalyze histone H4 acetylation, thereby driving resistance to BET inhibitors." (PMID 34564701, 2021). "We also found that the pharmacological targeting of the MAPK signaling pathway via IGF1R and ERK1/2 inhibitors was able to partially restore the sensitivity of HAT1-knockdown and HAT1-KO melanoma cells to BRAFi." (PMID 32371878, 2020). "Here, we showed that the genetic inhibition of histone acetyltransferase 1 (HAT1) in BRAF-mutant melanoma cells resulted in BRAFi resistance." (PMID 32371878, 2020). "Our results showed that common pathways that were upregulated in both HAT1-knockdown and HAT1-KO melanoma cells, includes TGF-β, Wnt, Ras, and MAPK pathways." (PMID 32371878, 2020). "In our study, we found that in melanoma cells with reduced HAT1 expression levels, IGF1R levels were upregulated, leading to the activation of MAPK/Ras signaling pathway and conferring BRAFi resistance." (PMID 32371878, 2020). "We also performed experiments to establish the clinical relevance of HAT1 during the development of BRAFi resistance in melanoma patients." (PMID 32371878, 2020). "We also confirmed that ~63% of progressed samples, from BRAF-mutant melanoma patients who experienced disease progression following BRAFi or BRAFi + MEKi therapy, showed significantly reduced HAT1 expression levels compared with matched pre-treatment samples." (PMID 32371878, 2020). "Using HAT1-KO cells, we performed a long-term survival assay and found that these melanoma cells showed resistance to both vemurafenib and dabrafenib." (PMID 32371878, 2020). "Overall, our results demonstrated that the loss of HAT1 expression resulted in the upregulation of both MAPK-independent and MAPK-dependent pathways, leading to the acquisition of BRAFi resistance in melanoma cells." (PMID 32371878, 2020). "Our results showed that phospho-ERK1/2 protein levels were significantly upregulated in both HAT1-knockdown and HAT1-KO melanoma cells." (PMID 32371878, 2020).
melanoma (continued). "To further fortify our results, we performed a soft-agar assay to determine the anchorage-independent growth abilities of HAT1-knockdown melanoma cells in the presence of vemurafenib." (PMID 32371878, 2020). "Our results showed that HAT1-knockdown BRAF-mutant melanoma cells were resistant to vemurafenib treatment compared with cells expressing a control NS shRNA." (PMID 32371878, 2020). "Melanoma cells expressing either NS or HAT1 shRNAs (HAT1 knockdown) were then tested for their sensitivity to the BRAFi vemurafenib, in a 3-(4,5-dimethylthiazol-2-yl)-2,5-diphenyl tetrazolium bromide (MTT)-based short-term cell-survival assay." (PMID 32371878, 2020). "We found that treatment with either the ERK or IGF1R inhibitors was able to restore sensitivity to vermurafenib in both HAT1-knockdown and HAT1-KO BRAFi-resistant melanoma cells, in both the soft-agar assay and in the clonogenic long-term survival assay." (PMID 32371878, 2020). "Our results showed that 7 out of 11 cases of progressed melanoma samples, from patients previously treated with BRAFi or BRAFi+MEKi, showed lower expression levels of HAT1 protein compared with their respective, matched, pre-treatment samples." (PMID 32371878, 2020). "Using quantitative immunofluorescence analysis of patient sample pairs, consisting of pre-treatment along with matched progressed BRAFi + MEKi-treated melanoma samples, HAT1 downregulation was observed in 7/11 progressed samples (~63%) in comparison with pre-treated samples." (PMID 32371878, 2020). "However, we did not observe any significant changes in TGFβ1 or beta-catenin protein levels in either HAT1-knockdown or HAT1-KO melanoma cells." (PMID 32371878, 2020). "Because HAT1-KO melanoma cells became BRAFi resistant during a clonogenic long-term survival assay, we next tested whether HAT1 expression was downregulated in clinical samples taken from patients who experienced disease progression following treatment with BRAFi or BRAFi+MEKi." (PMID 32371878, 2020). "We first knocked down HAT1 expression, using shRNAs in BRAF-mutant melanoma cell lines (A375 and SKMEL-28)." (PMID 32371878, 2020). "Our results showed that DUSP levels were downregulated only in HAT1-KO melanoma cells, whereas in HAT1-knockdown melanoma cells, the DUSP expression levels did not change significantly." (PMID 32371878, 2020). "HAT1 downregulation is associated with non-responsiveness of BRAFi and MEKi in melanoma patients, and HAT1 depletion drives resistance to BRAFi vemurafenib and dabrafenib by upregulating MAPK via IGF1R in melanoma cells." (PMID 35966590, 2022). "In addition, because increased IGF1R expression levels were identified in the nCounter PanCancer Pathway Panel for Gene Expression, in both HAT1-knockdown and HAT1-KO BRAF-mutant melanoma cells, we analyzed the mRNA levels as well as protein levels of phospho- and total IGF1R in these samples." (PMID 32371878, 2020).
atherosclerosis (4 papers, 2019 to 2026). A disease characterized by the build-up of fatty material and calcium deposition in the arterial wall resulting in partial or complete occlusion of the arterial lumen. "In inflammation-associated atherosclerosis, HAT1 correlates with upregulation of NADPH oxidase 5 (NOX5)." (PMID 37048148, 2023). "The aim of this study was to investigate the expression pattern of key histone acetyltransferase subtypes (p300, HAT1) in human atherosclerosis and to determine their role in mediating the upregulation of Nox5 in macrophages under inflammatory conditions." (PMID 31565149, 2019). "Indeed, the expression and function of HAT1 have been linked with diseases that affect the global population, such as cancer, viral infections and inflammatory diseases (COPD, atherosclerosis and ischemic stroke)." (PMID 37107673, 2023). "A dual role for HAT1 has been described in the development of atherosclerosis." (PMID 37107673, 2023). "However, HAT1 also seems to act as an anti-agent in atherosclerosis by facilitating the transformation of macrophages into foam cells, which reduces cholesterol accumulation and helps inhibit atherosclerosis development." (PMID 41535263, 2026). "Previous studies have established a correlation between HAT1 expression and function in immunoinflammatory diseases, including chronic obstructive pulmonary disease (COPD) and atherosclerosis, where the immune response plays an important role in pathogenesis and outcomes." (PMID 41535263, 2026). "HAT1 is a target of miR-486, thus regulating the expression of ABCA1, leading to the accumulation of cholesterol, consequent transformation into foam cells, and the development of atherosclerosis." (PMID 37048148, 2023). "Therefore, HAT1 plays an important role in immunoinflammatory diseases such as chronic obstructive pulmonary disease (COPD), atherosclerosis and the vascular disease related to ischemic stroke, in which the immune response also plays an important role in pathogeneses and outcomes." (PMID 37107673, 2023).
chronic obstructive pulmonary disease (4 papers, 2021 to 2026). A chronic and progressive lung disorder characterized by the loss of elasticity of the bronchial tree and the air sacs, destruction of the air sacs wall, thickening of the bronchial wall, and mucous accumulation in the bronchial tree. "The relationship between miR-486-5p and HAT1 has also been evaluated in the context of chronic obstructive pulmonary disease (COPD)." (PMID 35731367, 2022).
hepatocellular carcinoma (4 papers, 2022 to 2025). A malignant tumor that arises from hepatocytes. "Other lines of research have revealed a relationship between HAT-1 and hepatocellular carcinoma (HCC) treatment with cisplatin, which is commonly associated with drug resistance in patients with this cancer." (PMID 37107673, 2023). "It has been reported that HAT1 upregulated in hepatocellular carcinoma (HCC) facilitated HCC cell growth, and its knockdown could sensitize HCC cells to cisplatin-induced apoptosis." (PMID 40283998, 2025).
prostate carcinoma (4 papers, 2017 to 2025). A carcinoma that arises from epithelial cells of the prostate gland. "Other proteins found to be over-expressed in SCC are TTL12 and HAT1, previously reported to be associated with prostate cancer or lymphoma and esophageal squamous cell carcinoma progression, respectively." (PMID 29285267, 2017). "A recent study reported that histone acetyltransferase 1 (HAT1) is upregulated in prostate cancer cells and correlated to disease progression to CRPC." (PMID 40356745, 2025). "We further compared the HAT1 mRNA expression between PCa samples and normal tissues based on RNA‐sequence data from Chinese Prostate Cancer Genome and Epigenome Atlas." (PMID 34323404, 2021). "Genistein also increased the HAT1 enzyme and acetylation at the H3K9 position in prostate cancer cells." (PMID 35992599, 2022).
viral infections (4 papers, 2022 to 2023). "HAT1 overexpression is related, among other outcomes, to viral infections, inflammatory diseases, and cancer, where it is associated with poor prognosis and low survival." (PMID 36612223, 2022). "Because of the central role played by HAT1 in several physiological processes, HAT1 dysregulation is involved in a broad spectrum of pathologies, such as cancer, viral infections and inflammatory diseases." (PMID 37107673, 2023). "HAT1 expression and function in viral infections and immunoinflammatory and vascular diseases." (PMID 37107673, 2023). "The role of HAT1 has been also investigated in viral infections." (PMID 37048148, 2023). "Moreover, HAT1 has been proposed as a molecular target for restoring systemic immunity after viral infections, such as tuberculosis, even if its precise function in the process has still to be clarified." (PMID 37048148, 2023). "Histone acetyltransferase 1 (HAT1) is one of the Gcn5-related N-acetyltransferase family and a type B histone acetyltransferase, which is involved in cancer, viral infections, immunoinflammatory and vascular diseases." (PMID 38155235, 2023).
colon cancer (3 papers, 2013 to 2021). "In addition to HAT1 mutations, HAT1 overexpression is also frequent in multiple cancer types, including colon cancer, esophageal cancer, and lymphoma, exacerbating tumor malignancy." (PMID 34564701, 2021).
osteosarcoma (3 papers, 2021 to 2022). A usually aggressive malignant bone-forming mesenchymal neoplasm, predominantly affecting adolescents and young adults. "The potent tumor suppressor role of miR-377 in osteosarcoma is associated with the inactivation of histone acetyltransferase 1 (HAT1)-mediated Wnt signaling pathway." (PMID 35628648, 2022). "And apparently upregulation of miR-377 or inhibition of HAT1 prevented osteosarcoma progression via inactivating Wnt pathway thereby providing a therapeutic alternative." (PMID 35755302, 2022). "miR-377, which is a well-recognized tumor suppressor miRNA in many cancers, has been found to target HAT1 (histone acetyltransferase 1) in osteosarcoma." (PMID 35755302, 2022). "In Xia and colleagues' research, the analysis results showed upregulated HAT1 in osteosarcoma (OS), while miR-377 could promote the OS cell apoptosis and even mitigate tumor growth through inhibition of the Wnt signaling pathway via suppressing HAT1." (PMID 34326880, 2021).
COVID-19 (2 papers, 2021 to 2022). A disease caused by infection with severe acute respiratory syndrome coronavirus 2. "Transcriptome analysis studies conducted from patients with hypertension and DM associated with severe COVID-19 cases revealed that ACE2 expression was potentially regulated synergistically by various histone marks such as histone acetyltransferase 1 (HAT1), HDAC2, and lysine demethylase 5B (KDM5B)." (PMID 34691068, 2021). "One of the therapeutic targets that has gained prominence in recent years is HAT1, whose overexpression is known to be related to the development of various pathologies, such as infections caused by viruses (HBV, HIV, and COVID-19) or cancer." (PMID 36612223, 2022).
glioblastoma (2 papers, 2024 to 2026). The most malignant astrocytic tumor (WHO grade IV). "Under hypoxic conditions, the level of HIF2A protein in glioblastoma is regulated in a HAT1-dependent manner." (PMID 39068393, 2024). "Based on genome-wide analysis, relevant studies have determined that HAT1 is a type B histone acetyltransferase, a necessary gene upregulated in glioblastoma." (PMID 39068393, 2024). "It is indicated that HDAC4 has a better prognosis, while, accordingly, HAT1, HDAC1, HDAC3 and HDAC7 may have a poor prognosis for glioblastoma." (PMID 39068393, 2024). "Furthermore, five histone acetylation regulators were selected to be considered as the significant glioblastoma prognosis genes, in which HDAC1, HDAC3, HDAC4 and HDAC7 belong to histone deacetylases differently, HAT1 is a histone acetylase." (PMID 39068393, 2024).
glioma (2 papers, 2021 to 2022). A benign or malignant brain and spinal cord tumor that arises from glial cells (astrocytes, oligodendrocytes, ependymal cells). "Moreover, we identified that several underexplored LARs, such as ESC O 2, HAT1(KAT1), and LEF1, may have prognostic value in lower grade glioma patients and may be potential glioma biomarkers." (PMID 33718432, 2021).
Hypertension (2 papers, 2021 to 2023). The presence of chronic increased pressure in the systemic arterial system. "Therefore, we measured the expression of Histone Acetyltransferase 1 (HAT1) to determine the effect of HSD on the acetylation process among rats with a genetic predisposition to hypertension." (PMID 36707861, 2023). "Moreover, hypertension may mediate cell oxidative stress via mitochondrial dysfunction, which induces histone acetylation by a high level of HAT1, leading to apoptosis." (PMID 36707861, 2023).
lung adenocarcinoma (2 papers, 2016 to 2025). A carcinoma that arises from the lung and is characterized by the presence of malignant glandular epithelial cells. "HAT1 knockout inhibits DNA repair in lung adenocarcinoma cells, thereby increasing radiotherapy sensitivity." (PMID 41271679, 2025). "In this study, we found that HAT1 is highly expressed in lung adenocarcinoma and impairs patient survival." (PMID 41271679, 2025). "At most, the gene expression of a histone lysine methyltransferase, SMYD3, and a histone acetyltransferase, HAT1, was considerably increased among 21 and 11 lung adenocarcinoma cell lines, respectively." (PMID 27042856, 2016).
metastatic tumors (2 papers, 2022 to 2023). "In CRC, HAT1 cell localization changes significantly among normal tissue, primary cancer, and metastasizing cells; indeed, HAT1 cytoplasmatic localization is increased in primary and metastatic tumors compared to human normal colonic mucosa." (PMID 37048148, 2023).
Obesity (2 papers, 2024 to 2025). Accumulation of substantial excess body fat. "Yet, we cannot rule out the contribution of other epigenetics enzymes (e.g., EZH2, HAT1, LSD2, H3K4me3, H3K9me3, and H3K27me3), previously reported to be elevated in obese-MSCs, to alter mitochondrial gene expression and function imposed by obesity." (PMID 38824145, 2024).
cervical cancer (1 paper, 2021). A primary or metastatic malignant neoplasm involving the cervix. "HAT1 is upregulated in cervical cancer and is responsible for the induction of colony formation." (PMID 35096000, 2021).